SHH (sonic hedgehog signaling molecule)
Diseases named in the same sentence as SHH in open-access papers (continued):
Sharing a sentence is not in itself a finding about the gene and the disease.
cancer (continued). "Moreover, genes in the WNT, SHH, and BMP pathways such as WNT5A, FZD7, and FZD5, SHH, SMO, and GLI2 as well as BMP4 were likewise among the upregulated genes and were included in pathway of cancer gene set." (PMID 26998479, 2015). "The transcriptional regulation of TGF-β1 by GLI2 is a new extension to Sonic Hedgehog (SHH) and TGF-β1 cross-regulation and may provide insight into the detrimental elevation of TGF-β1 leading to pathogenesis in cancer and HIV infection." (PMID 22859956, 2012). "Abnormal activation of the Sonic hedgehog (SHH) pathway has been described in a wide variety of human cancers and in cancer stem cells (CSCs), however, the role of SHH pathway in gastric CSCs has not been reported." (PMID 21394208, 2011). "Expression levels of SHH, PTCH1, and sFRP1 mRNA in cancer samples were analyzed with real-time PCR." (PMID 20230186, 2010). "But the Gli family does not always act together on cancer cells, for example, nearly all BCCs express Gli1, but not Gli3 or SHH, suggesting that Gli1, which can be induced by SHH, may serve as the principal oncogenic agent." (PMID 39900571, 2025). "Their involvement in essential signaling pathways such as Wnt/β-catenin, SHH, Notch, PI3K/AKT, and MAPK underscores their importance in regulating cellular proliferation, differentiation, apoptosis, and migration, key processes that are often deregulated in cancer." (PMID 40952541, 2025). "Developmental pathways including Sonic Hedgehog (SHH), NOTCH and WNT signaling are the most activated pathways in PC cells, which have been experimentally demonstrated to be mechanistically connected with the cancer stemness features of PC and promote PC invasion, metastasis, and drug resistance." (PMID 37173787, 2023). "However, their effect on the sonic hedgehog (SHH) pathway has never been demonstrated in any cancer cells." (PMID 37407723, 2023). "Interestingly, our study found that overexpression of NKX6-1 modulates SHH pathway genes and promotes cancer stemness, indicating a novel reciprocal regulatory axis between NKX6-1 and SHH signaling in cancer." (PMID 33906647, 2021). "Second, lack of SHH driven ECM deposition may allow increased dissemination of cancer cells from the primary site to distant sites." (PMID 30108679, 2018). "Although early researchers considered SHH to be active in embryos and absent, or silent, in adults, recent data have recognized SHH as an active pathway during adulthood in pathological processes such as cancer or during tissue repair." (PMID 28962669, 2017). "However, the complex mitogenic roles of SHH provide one explanation of why there is no apparent increase in cancer incidence in ciliopathy patients." (PMID 27335639, 2016). "According to our data, SHH expression in cancer may not (only) constitutively activate the Ptc–Smo–Gli canonical pathway but rather support survival by blocking CDON apoptotic activity." (PMID 23940460, 2013). "Our observation of Bmi-1, SHH, Oct4, PSP and Snail expression only in the cancer stem cell component of a human brain malignancy may shed light on the dynamic nature of the cancer stem cell to exit the capacity to self renew as it differentiates into a daughter cell." (PMID 17140455, 2006). "However, the expression of the HDL-receptor, SCARB1, in SHH-driven cancers has not been studied." (PMID 29352211, 2018). "Besides SHH/GLI Wnt, Notch, and transforming growth factor β (TGF- β)/Bone Morphogenetic Protein (BMP) signaling are key among the pathways controlling epidermal lineage and homeostasis and many other cancer related pathways are expressed distinctively among BCC subtypes." (PMID 29137400, 2017). "Inhibition of Gli may be more effective than inhibition of Smo in preventing downstream SHh gene activation given evidence for non-canonical Gli activation independent of SHh in cancer cells and evidence that Gli is a target of other oncogenic signaling pathways." (PMID 27533453, 2016).
cancer (continued). "However, migration was not inhibited, suggesting that SHH signaling may mediate cancer-related phenotypes such as mesenchymal migration through Gli-independent mechanisms." (PMID 26512695, 2015). "Development of a candidate drug interfering with Hedgehog–CDON interaction could be of potential benefit to the large number of patients suffering from cancers with high SHH levels, but not currently responding to therapies aimed at antagonizing the Hedgehog signaling pathway." (PMID 23940460, 2013). "Similar pro-apoptotic effects of Fc-CDON3FbnIII were obtained with the colorectal HT-29, the pancreatic PANC-1, and the breast MDA-MB436 cancer cell lines, which all express CDON and SHH mRNA (Figure S6DE and not shown)." (PMID 23940460, 2013). "Although aberrant activation of SHH/GLI signaling leads to elevated expression of immunosuppressive factors like TGF-β1, a clear mechanism of cancer-induced TGF-β1 induction is still lacking." (PMID 22859956, 2012). "Moreover, the HH signaling is activated in CRC by ligand-dependent mechanisms with overexpression of SHH, as well as the SHH-GLI1 pathway but both pathways, canonical and non-canonical can co-exist in cancer context." (PMID 33691728, 2021).
CNS tumors (18 papers, 2019 to 2025). "Molecular profiling and biomarker discovery efforts are critical steps towards personalised medicine approaches in the treatment of SHH pathway-associated CNS tumours." (PMID 39568072, 2024). "Firstly, the majority of studies included are preclinical, providing valuable insights into the mechanisms and implications of SHH signalling and its interplay with other molecular pathways in CNS tumours." (PMID 39568072, 2024). "The integration of molecular insights with advanced technologies and clinical expertise holds great promise for developing more effective and personalised therapies for patients with SHH pathway-driven CNS tumours." (PMID 39568072, 2024). "In conclusion, Notch signalling's intricate regulation and crosstalk with SHH signalling contribute significantly to CNS tumour development and progression." (PMID 39568072, 2024). "In summary, highlighting the intricate interactions between SHH and Wnt signalling pathways in CNS tumours is crucial for understanding their roles in tumorigenesis and identifying potential therapeutic targets." (PMID 39568072, 2024). "By influencing cellular proliferation, differentiation and migration in CNS tumours, the SHH pathway has emerged as a promising target for therapeutic intervention." (PMID 39568072, 2024). "The complexity of the SHH signalling pathway and its interactions with other pathways in CNS tumours remains poorly understood, necessitating further research to bridge these knowledge gaps." (PMID 39568072, 2024). "In conclusion, The SHH signalling pathway plays a crucial role in the proliferation and growth of certain CNS tumours." (PMID 39568072, 2024). "The SHH signalling pathway, a crucial regulator of cellular proliferation, differentiation, and tumorigenesis, has been increasingly recognized for its role in the pathogenesis of CNS tumours." (PMID 39568072, 2024). "Currently, drugs that target SHH signalling pathways in CNS tumours can be categorised into SMO inhibitors, GLI inhibitors and SHH inhibitors." (PMID 39568072, 2024). "This CNS tumour comprises four molecularly defined subgroups (WNT, SHH, Group 3 and Group 4), defined through international consensus and which are identifiable by transcriptomic or methylomic signatures." (PMID 34230614, 2021). "Despite these insights, the precise mechanistic details of how SHH and the PAM pathway interact in CNS tumours remain unclear." (PMID 39568072, 2024). "Of note, WNT/SHH subgrouping was not widely used until the pronouncement of the 2016 WHO classification of CNS tumors." (PMID 36916326, 2023). "MB is mostly localized in the cerebellum with a peak incidence of around five years of age and is classified into four principal molecular groups (wingless activated (WNT), sonic hedgehog (SHH) activated, and non-SHH/WNT Group 3 and 4), according to the 2021 WHO Classification of Tumors of the CNS." (PMID 38136601, 2023). "With the addition of molecular pathology, the 2016 edition of the World Health Organization (WHO) CNS tumor classification classifies MB into four subgroups: wingless pathway (WNT), sonic hedgehog (SHH), Group 3, and Group 4, making the diagnosis and treatment of MB more individualized." (PMID 36452490, 2022).
CNS tumors (continued). "Additionally, targeting SMO, GLI, and SHH signalling in non-CNS tumours suggests potential applications in CNS tumours, underscoring the need for further research." (PMID 39568072, 2024). "In the new version of WHO classification of the CNS tumors, MBs not belonging to the WNT or SHH group are designated as “non-WNT/non-SHH”, which is a combination of the established molecular subgroups “non-WNT/non-SHH group 3” and “non-WNT/non-SHH group 4”." (PMID 36937322, 2023).
infection (9 papers, 2011 to 2025). The state of being infected such as from the introduction of a foreign agent such as serum, vaccine, antigenic substance or organism. "This time point was chosen as it precedes the onset of SHH expression and leads to widespread infection of the face." (PMID 40397886, 2025). "After injury and infection, enhanced SHH signaling attenuates the proliferative expansion of B cells, supports the formation of I cells, and enhances the differentiation of S cells, i.e. is part of the regenerative response to restore urothelial integrity." (PMID 40167323, 2025). "Interestingly, inhibition of NOTCH1 signaling resulted in elevated expression of infection-induced PD-L1 whereas inhibition of SHH signaling showed increased transcripts of JAG2 and NICD, markers for NOTCH activation." (PMID 27080341, 2016). "Together, these results indicate a counter-balance between the effects of infection-induced NOTCH1 and SHH signaling cascades to regulate CD4+CD25+FoxP3+ Treg expansion." (PMID 27080341, 2016). "Further, counter-regulatory roles of SHH and NOTCH1 signaling during mycobacterial-infection of human DCs was also evident." (PMID 27080341, 2016). "Using infection of human cerebral organoids to assess protein changes, we show CMV infection dysregulates localisation and expression of DYRK pathway (DYRK1A, DYRK1B) and SHH pathway (Shh morphogen, Gli2 transactivator, ULK3 kinase, and Rb tumor suppressor protein) proteins." (PMID 38504123, 2024). "Interestingly, infection-induced Th1-polarizing IL-12p70 was found to be SHH and NOTCH signaling dependent." (PMID 27080341, 2016). "In summary, establishing novel roles for SHH and NOTCH1 signaling pathways, we found mycobacteria-activated SHH signaling induces PD-L1 and COX-2-PGE2 to mediate the expansion of CD4+CD25+FoxP3+ Tregs whereas infection-induced NOTCH1 signaling was found to suppress the Treg expansion." (PMID 27080341, 2016). "We used lentiviral infection followed by clonal selection with plasmids for RNAi knockdown of Hsd17b7 to create cell lines with reduced levels of Hsd17b7 (approx. 80% reduced, data not shown) and then treated the lines with recombinant SHH, as done with the MEFs." (PMID 21912524, 2011).
adenocarcinoma (7 papers, 2006 to 2023). A common cancer characterized by the presence of malignant glandular cells. "The expressions of SHH and GLI1 were higher in adenocarcinoma clinical stages III and IV compared to stage II; in normal tissue, their expressions were minimal." (PMID 32867229, 2020).
nervous system diseases (6 papers, 2014 to 2025). "SMO, a key G protein-coupled receptor (GPCR) in the Sonic Hedgehog (SHH) pathway, promotes neuroprotection and recovery in neurological diseases." (PMID 39571157, 2024). "At the same time, the activation of the SHH signaling pathway is related to the progress of various tumors and nervous system diseases." (PMID 36056982, 2022). "The Sonic Hedgehog (SHH) signaling pathway is related to the progression of various tumors and nervous system diseases." (PMID 36056982, 2022). "Dysregulation of SHH occurs in a variety of neurologic disorders; therefore, activation of the SHH signaling pathway, which would enhance neurogenesis and gliogenesis, has been proposed as a potential therapeutic approach for treatment of these diseases." (PMID 25313834, 2014). "Our findings suggest that astrocytic SHH is a potential therapeutic target that could be used to restore disrupted BBB in patients with neurologic diseases." (PMID 25313834, 2014). "Our findings reveal novel mechanisms of BBB disruption by IL-1β, and suggest that SHH could be used therapeutically against various neurologic diseases." (PMID 25313834, 2014). "However, the abnormal SHH signaling pathway can lead to a variety of nervous system diseases." (PMID 34307464, 2021).
neurodegenerative disease (6 papers, 2021 to 2024). A disorder of the central nervous system characterized by gradual and progressive loss of neural tissue and neurologic function. "In SHH pathway, the deregulation of SMO-SHH signaling pathway can cause neurodegenerative diseases such as PD, and the activation of the SMO-SHH-GLI pathway has neuroprotective, anti-inflammatory and antioxidant properties." (PMID 39364348, 2024). "This mini-review will summarize the roles and mechanisms of the SHH pathway during the development of the central nervous system and neurodegenerative diseases." (PMID 34307464, 2021). "This mini-review has summarized that the SHH signal exerts a key function on neurodegenerative diseases and becomes a key factor in the normal development of the vertebrate central nervous system." (PMID 34307464, 2021). "Here, we summarize the role and mechanism of the SHH signaling pathway in the development of the central nervous system and aging-related neurodegenerative diseases." (PMID 34307464, 2021). "In this review, we will also highlight the potential of the SHH pathway as a therapeutic target for treating neurodegenerative diseases." (PMID 34307464, 2021). "At present, the SHH signaling pathway can be divided into the canonical signaling pathway and non-canonical signaling pathway, which directly or indirectly mediates other related pathways involved in the development of neurodegenerative diseases." (PMID 34307464, 2021). "Moreover, it is suggested that SHH pathway dysregulation may contribute to the pathogenesis of aging-related neurodegenerative diseases, such as AD." (PMID 39507054, 2024). "Hence, an in-depth knowledge of the SHH signaling pathway may open an avenue of possibilities for the treatment of neurodegenerative diseases." (PMID 34307464, 2021).
hematological malignancies (5 papers, 2014 to 2024). "SHH signalling is the most critical pathway regulated by primary cilia, which is activated in multiple PC-deficiency cancers such as skin, brain, liver, colon, breast, lung, prostate, and hematological malignancies." (PMID 37101292, 2023). "Further investigations should determine the clinical applications of modulating the SHh pathway in treatment of hematological malignancies." (PMID 24740159, 2014).
genetic disease (3 papers, 2005 to 2025). "Therefore, a profound understanding of how SHH signaling affects cerebellar development sheds light on novel therapeutic avenues for SHH-related genetic diseases." (PMID 35573667, 2022). "Thus, the importance of SHH signaling in the developing cerebellum has been increasingly recognized and research is focused on the pathway for the development of potential therapies for genetic diseases." (PMID 35573667, 2022).
neurodevelopmental disorder (3 papers, 2018 to 2024). A behavioral and cognitive disorder with onset during the developmental period that involves impaired or aberrant development of intellectual, motor, or social functions. "The analyses show that overactive SHH signaling causes the formation of ventral telencephalic progenitors and neurons instead of cortical cells and imply important ciliary functions in the pathogenesis of neurodevelopmental disorders." (PMID 35584663, 2022). "The SHH signaling pathway is crucial for mammalian brain homeostasis and its aberrant activation is responsible for neurodevelopmental disorders and MB formation." (PMID 38062245, 2024).
malformation syndromes (2 papers, 2009 to 2021). "Next, we classify the phenotypes of human malformation syndromes due to mutations in the major constituent genes of the SHH pathway." (PMID 34884862, 2021). "Mutations in the SHH gene itself also contribute to human malformation syndromes, as a series of related symptoms." (PMID 34884862, 2021). "In this review, we summarize the molecular mechanisms and role in embryonic morphogenesis of the SHH pathway, then classify the phenotype of each malformation syndrome associated with mutations of major molecules in the pathway." (PMID 34884862, 2021). "Consequently, the following anomalies are particularly important when considering the symptoms of human malformation syndromes caused by genetic defects in the SHH pathway." (PMID 34884862, 2021). "Interestingly, these craniofacial features are reversed in malformation syndromes associated with excess SHH signaling activity." (PMID 34884862, 2021). "Mutations in the transcription factor GLI3, a downstream target of Sonic Hedgehog (SHH) signaling, are responsible for the development of malformation syndromes such as Greig-cephalopolysyndactyly-syndrome (GCPS), or Pallister-Hall-syndrome (PHS)." (PMID 19829694, 2009).